ARMCX3 (armadillo repeat containing X-linked 3)
Description:
Regulates mitochondrial aggregation and transport in axons in living neurons. May link mitochondria to the TRAK2-kinesin motor complex via its interaction with Miro and TRAK2. Mitochondrial distribution and dynamics is regulated through ARMCX3 protein degradation, which is promoted by PCK and negatively regulated by WNT1. Enhances the SOX10-mediated transactivation of the neuronal acetylcholine receptor subunit alpha-3 and beta-4 subunit gene promoters.
Synonyms: ALEX3; GASP6; dJ545K15.2
Tractability: Antibody: UniProt predicts a signal peptide or a membrane-spanning region. PROTAC: ubiquitination databases record sites on it; its protein half-life has been measured.
Gene: Protein-coding gene on chromosome X (101,622,797 to 101,627,843, forward strand). Ensembl gene ENSG00000102401.
Subcellular location: Mitochondrion outer membrane; Cytoplasm; Nucleus
Subcellular location (Human Protein Atlas): Nucleoplasm; Cytosol; Golgi apparatus
Pathways (Reactome):
Signal Transduction: RAC2 GTPase cycle
Gene Ontology:
Molecular function: protein binding
Biological process: axonal transport of mitochondrion
Cellular component: mitochondrion; cytoplasm; mitochondrial outer membrane; nucleus; axon cytoplasm; cytosol
Homologues: Orthologues: macaque ARMCX3 (99% identical), mouse Armcx3 (97% identical), pig ARMCX3 (97% identical), guinea pig ARMCX3 (96% identical), rabbit ARMCX3 (95% identical), dog ARMCX3 (95% identical), rat Armcx3 (92% identical), tropical clawed frog armc10 (28% identical), zebrafish armc10 (27% identical), Caenorhabditis elegans Y67A10A.7 (15% identical). Paralogues in human: ARMCX1 (49% identical), ARMC10 (45% identical), ARMCX2 (40% identical), ARMCX4 (40% identical), GPRASP1 (27% identical), ARMCX6 (26% identical), ARMCX5 (25% identical), GPRASP2 (24% identical), ARMC12 (18% identical), GPRASP3 (17% identical).
Diseases named in the same sentence as ARMCX3 in open-access papers:
ARMCX3 is named in the same sentence as 15 diseases in open-access papers, as found by Europe PMC text mining. Sharing a sentence is not in itself a finding about the gene and the disease. The quoted sentences say what the papers report.
depression (1 paper, 2021). "A growing number of studies have suggested that the nAChR is related to nicotine addiction, cognition, depression, hyperactivity disorder, cancer, and AD; therefore, ARMCX3 may promote the progression of AD." (PMID 34912852, 2021). "A growing number of studies have suggested that the nAChR is related to nicotine addiction, cognition, depression, hyperactivity disorder, cancer, and AD; therefore, ARMCX3 may promote the progression of these diseases." (PMID 34912852, 2021).
diabetes (1 paper, 2021). "For example, both ARMC10 and ARMCX3 interact with the Miro/Trak2 complex in mitochondria and thus regulate mitochondrial function to inhibit the progression of AD, PD, diabetes, cancers, mitochondrial diseases, immune-related diseases, and other mitochondrial-related diseases." (PMID 34912852, 2021). "Therefore, ARMCX3 may inhibit the progression of diabetes by interacting with the Kinesin/Miro/Trak2 complex." (PMID 34912852, 2021).
Hepatic steatosis (1 paper, 2021). Steatosis is a term used to denote lipid accumulation within hepatocytes. "Hepatic steatosis was strongly reduced in the livers of ARMCX3-KO mice maintained on HFD." (PMID 33807672, 2021). "The protective effects of ARMCX3 downregulation on systemic metabolism and hepatic steatosis, especially under HFD, may be involved in the ability of ARMCX3 downregulation to protect against hepatocarcinogenesis." (PMID 33807672, 2021).
hepatocellular carcinoma (1 paper, 2021). A malignant tumor that arises from hepatocytes. "Given the relationship we observed between ARMCX3 and hepatic lipid metabolism in vivo, we determined the effects of fatty acids on ARMCX3 expression in hepatoma cells." (PMID 33807672, 2021). "Armcx3 was also found to promote hepatic cell proliferation through the interaction with Sox9, a known proliferation factor in hepatocellular carcinoma." (PMID 33807672, 2021). "In addition, overexpression of ARMCX3 promoted the clonality capacity of hepatoma cells, resulting in an increase in the size of colonies." (PMID 33807672, 2021). "We found, using co-immunoprecipitation assays, that ARMCX3 and SOX9 physically interact in hepatoma cells." (PMID 33807672, 2021). "We found that ARMCX3 is markedly upregulated in mouse liver in response to high lipid availability, and that hepatic ARMCX3 is upregulated in patients with NAFLD and hepatocellular carcinoma (HCC)." (PMID 33807672, 2021).
Insulin resistance (1 paper, 2021). Increased resistance towards insulin, that is, diminished effectiveness of insulin in reducing blood glucose levels. "In addition, ARMCX3 is related to the regulation of cholesterol, fatty acids, glucose metabolism, and muscle development or hypertrophy because ARMCX3 methylation causes the downregulation of HDAC7 and FYN, which lead to a low birth weight (LBW), insulin resistance, and T2D." (PMID 34912852, 2021).
liver cancer (1 paper, 2021). An epithelial or non-epithelial malignant neoplasm that arises from the liver. "Armcx3 is identified as a novel factor in meditating propensity to liver cancer in conditions of high hepatic lipid insults." (PMID 33807672, 2021). "We generated mice with genetically driven suppression of Armcx3, and we found that they were protected against experimentally induced hepatic cancer, especially in conditions of a high-fat diet." (PMID 33807672, 2021).
osteoporosis (1 paper, 2024). A condition of reduced bone mass, with decreased cortical thickness and a decrease in the number and size of the trabeculae of cancellous bone (but normal chemical composition), resulting in increased fracture incidence. "The essential genes PRKCB, GSDMD, ARMCX3, and CASP3 affected periodontitis and osteoporosis by involving the MAPK signaling pathway and the neutrophil extracellular trap formation." (PMID 38511766, 2024).
tumor (6 papers, 2013 to 2023). "Regarding the expression of p21, NTAL, EBP50 and ARMCX3, our results show the important role of senescence induction in tumor defense and underline the relevance of cell cycle regulator p21 and p21-mediated senescence." (PMID 35492321, 2022). "The cluster of upregulated genes contained those mainly involved in metabolism such as GGT1 (gamma glutamyl transferase 1), vesicular traffic/secretion such as SYT13 (synaptotagmin XIII) and tumor suppression such as ARMCX3 (armadillo repeat-containing X-linked protein 3) and ARMCX6." (PMID 30337535, 2018). "Alex3 (encoded by ARMCX3) regulates migration and invasion in tumor cells, functions which are also critical for placentation and subsequent fetal outcomes, including fetal growth." (PMID 29335024, 2018). "We observed that DEN treatment of ARMCX3-KO mice resulted in decreases in the tumor number, average tumor size and maximum tumor size compared with those of control littermates, indicating that ARMCX3 deficiency had a marked and significant protective effect in HFD-fed mice." (PMID 33807672, 2021). "For NTAL, ARMCX3, p21, and EBP50 the percentage of positive tumor cells showed a statistically significant prognostic effect." (PMID 35492321, 2022). "We examined the impact of ARMCX3 invalidation on the phospho-AKT/AKT, phospho-S6/S6, phospho-ERK/ERK and phospho-p38/p38 ratios in non-tumor tissue from DEN-treated LFD and HFD-fed mice." (PMID 33807672, 2021). "ARMCX3 invalidation did not affect apoptosis of hepatocytes in non-tumor regions, but tumor regions from ARMCX3-KO mice fed HFD showed markedly more cleaved caspase-3 relative to those of control mice." (PMID 33807672, 2021). "Our in vitro results do not allow us to rule out the possibility that ARMCX3 controls tumor progression by enhancing proliferation and invasiveness." (PMID 33807672, 2021). "p38 MAPK activation tended to be lower in tumor tissues, but irrespective of invalidation or not of ARMCX3." (PMID 33807672, 2021). "Our results indicated that ARMCX3 depletion did not affect markedly cellular proliferation in tumor regions, although Ki67 and BrdU positive staining tended to be higher in ARMCX3-KO mice that were fed HFD." (PMID 33807672, 2021).
cancer (3 papers, 2013 to 2021). A tumor composed of atypical neoplastic, often pleomorphic cells that invade other tissues. "A previous study suggested that the nAChR is related to cancers; therefore, ARMCX3 may promote the progression of cancers." (PMID 34912852, 2021). "Therefore, ARMCX3 may inhibit the progression of cancers by interacting with the Kinesin/Miro/Trak2 complex." (PMID 34912852, 2021).
nervous system disorder (1 paper, 2022). A non-neoplastic or neoplastic disorder that affects the brain, spinal cord, or peripheral nerves. "On the other hand, the ARMC proteins including ARMC4, ARMC5, ARMC6, ARMC7, ARMC8, ARMC10, and ARMCX3 regulate the Wnt signaling pathway leading to specific nervous system disorders." (PMID 36553564, 2022).
ARMCX3 also shares sentences with these, for which no sentence is quoted: epithelial carcinomas (1 paper); gastric tumors (1); mitochondrial disease (1); nicotine addiction (1); periodontitis (1).